IL10 (interleukin 10)
Diseases named in the same sentence as IL10 in open-access papers (continued):
Sharing a sentence is not in itself a finding about the gene and the disease.
tumor (continued). "Macrophage phenotype becomes shifted towards the immunosuppressive M2-like subset by tumour-derived cytokines such as IL-4, IL-10, and IL-13." (PMID 36325338, 2022). "On the one hand, IL-10 inhibits the inflammatory Th17 cells and macrophages and thereby facilitates tumor onset and progression." (PMID 36531027, 2022). "Visceral adipose tissue (VAT)-associated CD4+ Tregs are found in the omentum, producing high levels of IL-10 to constitute Treg subpopulation and then suppressing the anti-tumor immune system." (PMID 36503580, 2022). "By blocking cell-mediated immune responses and inflammatory reactions, IL-10 can promote carcinogenesis by limiting the development of an adequate antitumor response against tumor cells." (PMID 35919032, 2022). "In contrast, IL-10 is regarded as an important product of M2 macrophages, and plays an important role in tumor growth and development." (PMID 36291890, 2022). "Based on the immunosuppressive ability of IL-10 in tumor immunity, therapeutic strategies targeting the IL-10 signaling pathway have evolved considerably in cancer immunotherapy." (PMID 35177742, 2022). "High infiltrations of IL-10+ TAMs cause immune effector cells such as CD8+ T cells and NK cells to be fatigued or dysfunctional, depriving them of their active role in anti-tumor immune responses." (PMID 36510315, 2022). "It has been proven that high levels of IL-10 in the tumor microenvironment facilitate tumor rejection by potentiating the cytotoxicity of T lymphocytes." (PMID 36132125, 2022). "In the current study, most TAM cells in tumor microenvironment exhibited the characteristics of M2 macrophages with the high expression of IL10, which functioned by inhibiting the immune response in the tumor microenvironment." (PMID 36699091, 2022). "It re-energize the immune system to attack the tumor cells by lowering IL-10 levels and promoting the manufacturing of IFN-γ in the tumor." (PMID 36298611, 2022). "Immunosuppressive IL-10 inhibits the differentiation and activation of DCs, which are key activators of anti-tumor effector cells of the adaptive immune system, including cytotoxic CD8+ T cells." (PMID 35154142, 2022). "This was consistent with an increase of IL-10 and expression level of FoxP3 in WT mice subjected to MC38 tumor injection, as compared to IL-10 and FoxP3 levels in the GCSFR−/− mice." (PMID 36033452, 2022). "The activation of TGF-β and IL-10 play an immunosuppressive role in the tumor microenvironment, while IL-2 can enhance the immune response of cancer patients." (PMID 36476246, 2022). "Tumor cell-released autophagosomes convert macrophages into anti-inflammatory M2-like phenotypes, characterized by the expression of PD-L1 and IL-10." (PMID 36233088, 2022). "TAMs exert pro-tumor and immunosuppressive functions by secreting IL-10 and TGF-β, VEGF, expressing PD-1, and depleting arginine to suppress T cells’ anti-tumor function." (PMID 36510315, 2022). "Apart from FasL, cytokines such as IL-10 and IL-6, have been demonstrated to play important roles in immunosuppression and promote tumor growth." (PMID 36387244, 2022). "Phosphorylation of STAT3 contributes to the deposition of collagen and release of IL‐10 and IL‐4 in tumours." (PMID 36178087, 2022). "CTCL patients had higher circulating levels of IL-6, IL-8, IL-10, TGFβ, PGE2 and MMP7 which are factors released by tumor-associated macrophages in tumor microenvironment." (PMID 36059695, 2022). "The IL-10 family consists of six cytokines with IL-10, IL-19, IL-20, IL-22 and IL-26 described as tumor promoting." (PMID 36611932, 2022). "More specifically, MMP-9 expression was positively correlated with IL-10 (a TAM marker), which is often associated with tumor immune evasion." (PMID 35178444, 2022). "In particular, some tumor-derived molecules, such as CSF-1 and IL-10, stimulate a considerable proportion of TAMs to differentiate into M2 macrophages." (PMID 35875135, 2022).
tumor (continued). "M2 macrophages secrete some anti-inflammatory factors, such as IL-4, IL-6, and IL-10, which negatively regulate the immune response in tumours." (PMID 35923703, 2022). "Among the immunosuppressive cytokines, IL-4, TGFβ and IL-10 are the most representative at the tumor site, contributing to CAR-T cell dysfunction." (PMID 39086964, 2022). "TGF-β, IL-10, prostaglandin E2, indoleamine 2,3-dioxygenase (Ido), and adenosine are examples of immune-suppressive substances that tumor cells can upregulate or release." (PMID 36703982, 2022). "Targeting DCs with lipoprotein and CpG ODN TLR agonists combined with tumor antigen decreased the production of immunosuppressive cytokine IL-10 while increasing IL-12 production from DCs." (PMID 35740589, 2022). "In contrast, recurrent tumors contain many immunosuppressive tumor-associated macrophages (TAMs) and Treg cells and the cytokines VEGF, IL-1β, IL-6, IL-10, and TGF-β, which suppress CD8+ T cells." (PMID 36685898, 2022). "IL-10 shows both tumor-promoting and tumor-suppressive effects in the development and pathogenesis of tumors." (PMID 35493517, 2022). "IL-10 can stimulate tumor proliferation and metastasis via suppression of the proliferation and activity of T cells." (PMID 36544523, 2022). "Strikingly, M-HIFU debris contained severely diminished absolute protein levels of TGF-β and IL-10 as compared to untreated control tumor tissue." (PMID 36569907, 2022). "Regulatory B cells (Bregs), on the other hand, are thought to facilitate tumor activity by secreting immunosuppressive substances including IL10 and/or TGF-β." (PMID 35392957, 2022). "These polarized TAMs usually express M2 macrophage markers and cytokines, such as mannose receptors (CD206), scavenger receptor (CD163), VEGF, and IL-10, and exhibit tumor-supporting effects, and are hence called M2-like TAMs." (PMID 35844605, 2022). "In contrast, the level of IL10 has been shown to be positive correlated with the intensity of tumor proliferation and apoptosis." (PMID 36555251, 2022). "In contrast, M2 is the alternative phenotype and activated by IL-4 and IL-10, which stimulate tumor promotion and metastasis by various mechanisms." (PMID 35757756, 2022). "IL-10 was demonstrated to suppress the production of IFN-α in the HNSCC tumor microenvironment, along with other factors." (PMID 36143043, 2022). "Canonical pathways identified by IPA included the tumor microenvironment, IL-10 signaling, airway pathology, granulocyte adhesion, and wound healing." (PMID 35864532, 2022). "IL-10 is believed to enhance tumor immune escape by reducing the antitumor immune response in the microenvironment, which is indicated by the positive correlation between IL-10 levels and the poor prognosis of patients." (PMID 35974992, 2022). "In ccRCC patients, tumor-infiltrating mast cells secret IL-10 and TGF-β to decrease anti-tumor immunity, leading to a worse prognosis." (PMID 36588797, 2022). "Although IL10 is a crucial immunosuppression agent, its role in cancer pathogenesis and development is complex and its action as a tumour‐promoting agent or an inhibitor needs to be clarified." (PMID 36433652, 2022). "As expected, blockade of either CSF1R (in CAFs), or MIP2 (in CAFs), or CXCR2 (in macrophages) enhanced the IL-12/IL-10 expression ratio in the latter, which was further corroborated with enhanced cytotoxicity against tumor cells." (PMID 35315360, 2022). "CD163+ M2 macrophages have been suggested to counteract tumor immunity by increasing immunosuppressive mechanisms including PD-L1 and IL-10 expression." (PMID 35204426, 2022). "In contrast, Th2 cells secrete anti-inflammatory factors such as IL-4, IL-5, and IL-10 to weaken the anti-tumor immune response." (PMID 35646059, 2022). "The two members of the tumor-derived IL family that have received the most research attention are IL-1 and IL-10, both of which are crucial in the development of tumors." (PMID 36497444, 2022).
tumor (continued). "In GBM, immunosuppressive cytokines like TGF-β and IL-10, are dominant in tumor immune microenvironment (TIME), which inhibit NK cells directly or indirectly by inducing other immunosuppressive factors." (PMID 35803912, 2022). "In cancer literature, IFNγ induction and IL-10 suppression in Treg appears to be an early requirement for Treg to properly mediate an anti-tumor environment, clear more tolerant Treg from their surroundings and boost anti-tumor immunity." (PMID 36558773, 2022). "In conclusion, IL-10 is responsible for inhibiting tumor development, tumor growth and formation of metastases." (PMID 34152493, 2022). "It was reported that tumor-infiltrating B cells contributed to tumor growth and progression through the production of cytokines, such as IL-10, that inhibit antitumor immunity, although the functional role of B cells in cancer is poorly understood." (PMID 35552285, 2022). "A correlation was also observed between IgG4 staining and tumor expressed IL-10 (r = 0.0.488, p = 0.000), and IL-4 (r = 0.262, p = 0.001), as well as between IL-10 and tumor stage (IL-10 r = 0.254, p = 0.016)." (PMID 35255925, 2022). "Smaller tumor size was detected in E7&IL-24 (P < 0.001), E7 (P < 0.01), and IL-24 (P < 0.05) groups when coupled with anti-IL-10 compared with isotype analogs." (PMID 35752792, 2022). "Following this, M1-like macrophages induced tumor death via secreting IL-6, IL-10, IL-12, and TNF-α." (PMID 36518255, 2022). "Other potential prognostic biomarkers, such as IDO1, IL-8, IL-10, and TGF-β, have been reported to be associated with the therapeutic response and tumor stage in EC." (PMID 36119033, 2022). "Macrophages secrete TGF-β and IL-10 to convert Th1 cells into Th2 cells, thus reversing the anti-tumour effects of CD8+ cytotoxic T cells and CD4+Th1 cells." (PMID 35591854, 2022). "Most neoplastic cells and tumor-associated cells in the TME secrete factors that block the activation of NK cells, such as IL-6, IL-10, IDO, TGF-β, and prostaglandin E2 (PGE2), through downregulating NK cells activating receptors including NKG2D." (PMID 36072957, 2022). "Tumor-derived factors (such as IL-6, IL-10, and VEGF) impede DC maturation and, as a result, their ability to serve as APCs." (PMID 36703982, 2022). "IL6 and IL10 were known to be key pro-tumor cytokines that exerts multiple functions in the development of liver tumors, including promoting proliferation, EMT, angiogenesis, anti-apoptosis, and immune surveillance evasion." (PMID 36238304, 2022). "TAMs are able to inhibit the action of cytotoxic T-cells via IL-10 secretion and support regulatory T-cells, thus leading to immune evasion and tumour proliferation." (PMID 36325338, 2022). "IL-10 secreted by M-MDSC plays a role in mediating tumor metastasis and suppressing immune response." (PMID 35999614, 2022). "For example, CSC-derived IL-10 and IL-6 were demonstrated to potentiate a pro-tumor phenotype of GAM." (PMID 36570441, 2022). "Recently, it was found that GABA secreted by B cells promotes the differentiation of monocytes into anti-inflammatory macrophages, which secrete IL-10 and suppress the anti-tumor response of CD8+ T cells." (PMID 35965506, 2022). "Many immunosuppressive factors, such as IL-10, TGFβ, and IL-6 produced by MDSCs, are able to induce stem cell properties in various tumor cells." (PMID 35757002, 2022). "Our data indicate that M-HIFU ablation attenuates the anti-inflammatory cytokines TGF-β and IL-10 within the tumor debris." (PMID 36569907, 2022). "MDSCs can impair the function of DCs, NK cells, and CTLs by overexpressing RONS, releasing IL-6 and IL-10, or depleting L-arginine (L-Arg), thus facilitating tumor escape." (PMID 35733919, 2022).
tumor (continued). "Tumor cell-released autophagosomes are sufficient to suppress the antitumor immune response in the mouse by inducing IL-10-producing B cells through high-mobility group B1 (HMGB1)." (PMID 36233088, 2022). "Conversely, IL-10 has been reported to have potent anti-tumor effects via inhibiting macrophages and angiogenic factors and activating CD8+ T cell." (PMID 35493517, 2022). "Immunosuppressive myeloid cells in the tumor microenvironment play a major role in suppressing tumor immunity via the production of arginase, IL-10, and others." (PMID 35878391, 2022). "IL-10 secretion represents the M2-type polarization of TAMs and its inhibitory role in the anti-tumor immune response." (PMID 36510315, 2022). "As a well-known anti-inflammatory cytokine, IL-10 inhibits antitumor immune responses by inhibiting a variety of effector molecules and tumor cells." (PMID 35681453, 2022). "Meanwhile, the IHC assay demonstrated that the expressions of CXCL14, PD-L1, and IL-10 were decreased in tumor tissues of mice treated with si-CXCL14." (PMID 35669852, 2022). "Usually, M2 or alternatively activated macrophages are activated by IL-4, IL-10, IL-13, and glucocorticoid hormones, express high levels of IL-10 and low levels of IL-12, and facilitate tumor progression." (PMID 35928634, 2022). "After extracting TAMs from mouse-bearing tumor tissue, we found that IL-10 and TGF-β was upregulated and TNF- α was downregulated in the silent ALKBH5 group." (PMID 35982895, 2022). "Regulatory B cells produce anti-inflammatory cytokines such as interleukin (IL)-10 to negatively regulate the immune response and play an anti-tumor role." (PMID 35051904, 2022). "In the tumor microenvironment, IL-10 is required for proper T cell function, immune surveillance, and suppression of cancer-associated inflammation." (PMID 36461062, 2022). "In another study, IL-10 as an anti-inflammatory cytokine was significantly increased, whereas Tumor necrosis factors TNF-α and IL-6 decreased following calorie restriction." (PMID 36364892, 2022). "The same treatment caused IL-2 serum levels boosting (578 pg/ml) compared with untreated tumor-bearing mice that exhibited values of 185, 107, 30, and 52 pg/ml for IL-2, IL-4, IL-10, and IFN-γ, respectively." (PMID 35845806, 2022). "Elevated levels of G-CSF, IL-6 and CXCL13, and B cell counts were associated with 4T1 growth, whereas CCL17, CXCL10, total myeloid cells, CCL2, IL-10, CXCL1, and Ly6Cintermediate monocytes were associated with CT26 tumour development." (PMID 35226704, 2022). "HIF2A upregulates stem cell factor expression to recruit tumor-infiltrating mast cells and increase levels of cytokines interleukin-10 and transforming growth factor-β, resulting in an immunosuppressive tumor microenvironment." (PMID 35659268, 2022). "The M2 phenotype forms the majority of TAM population in iCCA, having anti-inflammatory and pro-tumor functions mediated by the secretion of anti-inflammatory cytokines, including IL-4, IL-10, IL-13, and TGF-β." (PMID 35433771, 2022). "M2c induced by glucocorticoids, TGF‐β and IL‐10 and support induction of Tregs, correlate with tumour progression and poor prognosis." (PMID 35344301, 2022). "Mediators released by tumor-infiltrating lymphocytes, such as Th2 cells and Treg cells (producing IL-4 and Il-10), and by tumor cells (IL-10, TGFβ, and PGE2) activate an immunosuppressive program in TAMs." (PMID 35664746, 2022). "Tumor cells themselves can also secrete anti-inflammatory cytokines, such as IL-10 and TGF-β, as well as promote the generation of Treg and produce FAS-ligand to induce apoptosis of activated T cells." (PMID 36497422, 2022). "IL-10 inhibits tumor growth and progression, modulates apoptosis, and inhibits angiogenesis during tumor regression." (PMID 36289922, 2022). "MDSCs have been shown in murine cancer models to be the primary source of IL-10 within the tumor microenvironment." (PMID 36031601, 2022).
tumor (continued). "IL-1 β/ IL-8 is considered to be a cytokine promoting tumor formation, and IL-10 is a cytokine inhibiting tumor formation." (PMID 35449547, 2022). "Conversely, a study on Il10fl/fl/FIC mice have shown that the deletion of IL-10 from Tregs triggered more severe inflammation, leading to enhanced tumor formation and growth." (PMID 35733919, 2022). "In the EL-4 tumour model IL-10 produced by macrophages increases in ascitic fluid in line with progression of disease and correlates with increased TGF-β produced by the cancer cells." (PMID 34727230, 2022). "Previous studies have shown how the release of IL-10 from the tumor downregulates the expression of CD40 on DCs and DC precursors, suppressing their maturation and function." (PMID 36230990, 2022). "TGF-β aids in Treg cell differentiation to enhance cancer development, while IL-10 is an immunosuppressive factor, leading to the immune escape responses of tumor cells." (PMID 35889289, 2022). "The salivary protein results showed that various inflammatory markers were higher in the saliva of tumor patients with a trend of increased IL-10, IL-4, and IL-8; MCP-1; TNF-α; and VEGF levels observed, probably linked with the disease." (PMID 34251535, 2022). "Surgical tumor resection can induce immunosuppressive activities by inducing pro-inflammatory and pro-tumorigenic cytokines such as IL-1β, IL-6, IL-10 CCL-2 and TGF-β, which recruit immunosuppressive cells such as MDSCs." (PMID 36611932, 2022). "Our data demonstrated that metabolic reprogramming of terminally exhausted CD8+ T cells by IL-10 efficiently enhances anti-tumor immunity." (PMID 36494694, 2022). "CCL22 promotes the infiltration of Treg cells to the tumor, releasing IL-10, which suppresses the antigen presentation function of dendritic cells and the anti-cancer response of CD8+ T cells." (PMID 35565420, 2022). "Tregs in the blood and tumor had reduced IL-10 production after NEO, suggestive of a lower suppressive capacity." (PMID 36509285, 2022). "We differentiated these BMDMs for 6 days toward a pro-tumor (M2) phenotype using M-CSF, interleukin-4 (IL-4), and IL-10 and examined the effect of olaparib on these M2 macrophages." (PMID 36223740, 2022). "Recently, IL-10+ plasmablasts and IL-10+ B cells have been recovered from tumor-draining lymph nodes and tumor, where tumor patients have demonstrated a higher level of IL-10+ Bregs." (PMID 36091114, 2022). "Cytokine analysis can be used for VRL diagnosis; the amount of IL-10 derived from tumor cells can be measured and used to calculate the IL-10/IL-6 ratio." (PMID 36362676, 2022). "It has been classically considered an immunosuppressive factor that promotes tumor growth, while recent studies showed exogenous IL-10 administration can induce anti-tumor effects by promoting CD8 T cell-mediated anti-tumor immunity." (PMID 34502325, 2021). "Under the influence of tumor-derived factors, TAMs can secrete a series of cytokines, including IL-10, TGF-β, and prostaglandin 2 (PGE2), to further inhibit T cell-mediated immune responses and establish a self-proliferative immunosuppressive TME." (PMID 34926295, 2021). "Tumor-derived exosomes have been shown to induce PD1+ macrophages to produce IL-10 and inhibit the function of CD8+T cells." (PMID 34290608, 2021). "From the day 8 after tumor implant, the mice were intratumorally injected with different amount of IL-10." (PMID 33717103, 2021). "Subsequent reports further revealed that IFN-γ and IL-10 are required for the production of both TGF-β and IL-10 by MDSC in tumor-bearing mice." (PMID 33430105, 2021). "Tregs produce various cytokines, such as TGFβ and IL10, which induce immunosuppression and tumor aggravation." (PMID 33535613, 2021). "Next, we focused on one distinctive gene cluster that contained transforming growth factor beta 2 (TGFB2) and interleukin-10 (IL10), which appeared to be driven by the recurrence of selective copy number gain in multiple tumor types." (PMID 34344966, 2021).